CD24 (CD24 molecule)
Diseases named in the same sentence as CD24 in open-access papers (continued):
Sharing a sentence is not in itself a finding about the gene and the disease.
cancer (continued). "Eight mRNA markers (MYC, VEGF, CDX2, CD133, CEA, CK19, EpCAM, and CD24) were found to be more abundant in EVs derived from cancer cell lines compared to control cell lines." (PMID 32042310, 2020). "A meta-analysis of 28 studies revealed that CD24 is overexpressed in 68% of human cancers, and CD24 expression was correlated with a higher self-renewal ability, more metastases, and a poor prognosis." (PMID 33260974, 2020). "Evaluation of cancer stem cells (CSCs) parameters showed a dose-independent significant decrease in CD24 expression by 40.5% (p < 0.001) and 29% (p < 0.05) in treated groups compared to the control group." (PMID 32204409, 2020). "The CD24/siglec-10 signaling pathway protects cancer cells from the immune system, indicating a potential target for cancer immunotherapy." (PMID 32889432, 2020). "Using flow cytometry, we observed a statistically significant increase in the percentage of cancer cells that were positive for CD24, CD49f, and CD326 in JL mice." (PMID 32581213, 2020). "CD24 is a small sialoglycoprotein expressed on malignant cells where it is thought to be a cancer stem cell marker." (PMID 32937961, 2020). "Researchers have designed novel experimental drugs namely, Thiostrepton, whose pharmacological action consists of targeting the sonic Hedgehog signaling, Thiostrepton suppresses the population of CD44+/CD24− cancer stem cells (CSCs) of TNBC cell lines." (PMID 32245065, 2020). "We successfully derived FTEC with the expression of the normal stem cell markers (LGR5, SSEA3, and SSEA4), cancer stem cell markers (CD24, CD44, CD117, ROR1, CD133, and ALDH), and characteristics of stem cell." (PMID 32035490, 2020). "There was an inverse correlation between the expression of XIST and cancer stem cell (CD44 + /CD24−) population." (PMID 32943985, 2020). "CD24 is a cell-surface glycoprotein that is highly glycosylated and was shown to mediate rolling leukocytes and cancer cells." (PMID 32575485, 2020). "Haloperidol was associated with a significant decrease in CD24 and CD44, both of which have been related to cancer stem cells." (PMID 33322363, 2020). "In monolayer cells, the expression of the cancer stemness marker CD24 was relatively concentrated on the membrane in spheroid cells and SOX2 expression was mostly confined in the nucleus." (PMID 32457900, 2020). "CD24 is expressed by neutrophils and various cancer cells and the binding of the binding of CD24 onto P-selectin is not yet clarified." (PMID 32575485, 2020). "CD44 and CD24 expression, as cancer stem cell markers, were elevated in only WT liver with CCl4 administration." (PMID 33168815, 2020). "CTCs were identified as HLA+ (a human-specific marker), and CD44+CD24- cells indicate cancer stem cells." (PMID 33035223, 2020). "To assess the stem cell property of the gene-transfected and parental cells, we evaluated the expression levels of previously reported marker genes of CSCs in several cancers, such as CD24, CD26, and CD133 by qPCR analysis." (PMID 33008481, 2020). "Flow cytometry revealed expressions of normal stem cell markers (SSEA3, SSEA4, and LGR5) and cancer stem cell markers (CD24, CD44, CD117, ROR1, and CD133)." (PMID 32035490, 2020). "Evaluation of CSCs parameters in rat carcinoma cells demonstrated a dose-dependent significant decrease in CD24 and EpCam expression in treated groups, when compared to the control group." (PMID 33375383, 2020). "In treated rat carcinomas, we found significant caspase-3, Bax, and Bax/Bcl-2 expression increases; on the other side, a significant down-regulation of Bcl-2, Ki67, CD24, ALDH1, and EpCam expressions and MDA levels." (PMID 33375383, 2020). "Cancer stem cells (CSCs) were quantified by flow cytometry usinganti-CD24-FITC and anti-CD44-APC antibodies and propidium iodide." (PMID 31384244, 2019).
cancer (continued). "Different morphological structures were shown to represent transcriptionally distinct tumor cell populations differing in the number of CD44+CD24− cancer stem cells, epithelial and mesenchymal features, and enrichment of cancer invasion signaling pathways." (PMID 31344926, 2019). "Overexpression of SPAG5 in MDA-MB-231 cells increased the sphere-forming ability and the population of CD24-ESA+ cancer stem cells (CSCs), while SPAG5 knockdown had the opposite effects on Hs-578t cells." (PMID 30736840, 2019). "KrasG12D/p53loss induces cancer stem cell traits, with increased CD24, EpCAM, and CD133 expression as seen in advanced metastatic PCA." (PMID 30467381, 2019). "Activated CD24 induces Wnt signaling to induce cancer stemness in our mouse model, suggesting CD24/P-selectin inhibitor as a novel chemotherapy agent for metastatic PCA." (PMID 30467381, 2019). "Numerous studies have shown CD24 overexpression and its prognostic significance in multiple cancer types." (PMID 31244889, 2019). "We isolated CD44+/CD24- cells from the normal cancer cells with MACS and detected CD44 and CD24 expression to determine CD44 purity by flow cytometry." (PMID 31612865, 2019). "CD24 showed a significant association with pT- and UICC-stage (p = 0.0039 and 0.0057, respectively) for cancers of the oral cavity." (PMID 31661833, 2019). "Compared to monolayer condition, cancer stem cell marker CD24 and EGFR decreased in vivo from 70% to 35% and 100% to 25%, respectively." (PMID 31527554, 2019). "CD24 is present in a variety of cell types in mammalian organisms such as hematopoietic cells and cancer cells." (PMID 31624236, 2019). "Several studies have shown that CD24 expression induces cancer progression in various cancers with clinical recurrence and poor prognosis." (PMID 31614769, 2019). "The accumulation of CD24+ cancer cells on only one part of the solid tumor suggests that it is possible to design new drugs to target a subpopulation of cancer cells, for example as in this case, cancer stem cells with higher metastatic potentials." (PMID 30728024, 2019). "A decrease in CD24 of the cancer cell lines in co-culture with the CM-MSCs showed a reduction of the cancer tumorigenicity." (PMID 31351482, 2019). "CD24 is a cell adhesion molecule expressed on a variety of cells, such as neural cells and cells of the adrenal medulla, and in several cancers including NB." (PMID 31191243, 2019). "PDX tumors grown in the presence of obASCS in SCID/beige mice had increased circulating HLA1+ human cells as well as increased numbers of CD44+CD24− cancer stem cells in the peripheral blood." (PMID 31118047, 2019). "The high rate of CD24 amplification among multiple cancer types satisfies major criteria of CD24 as a bona fide oncogene." (PMID 31244889, 2019). "Microarray analyses of primary PCA cells derived from these models identified several cancer stemness genes including CD24, EpCAM, and CD133 upregulated by KRASG12D." (PMID 30467381, 2019). "Cytometry analysis of the proportion of cancer stem cells (CD44+/CD24-) isolated with MACS was > 99%." (PMID 31612865, 2019). "Taken together, these data demonstrate that obASCs are promoting EMT, through downregulation of CD326 in tumors, increasing HLA+ CTCs enriched for the cancer stem cell maker CD44+CD24−, and have increased lung metastases." (PMID 31118047, 2019). "Recent data demonstrated the therapeutic potential of CD24 blockade with monoclonal antibodies which promoted the phagocytic clearance of CD24+ cancer cells in vitro and in vivo." (PMID 31801627, 2019).
cancer (continued). "CD24-CAR-NK-92 cells specifically produced high amounts of IFNγ upon target presentation by cancer cells." (PMID 30717444, 2019). "CEA and CD24 are adhesion proteins that can have a macroscopic impact in terms of cancer progression and metastasis." (PMID 31614769, 2019). "We have demonstrated that inhibiting the HH pathway is related to a reduction of cells with the cancer stem cell related phenotype (CD44+/CD24−), less sphere forming capability and more radiosensitivity." (PMID 31200527, 2019). "In contrast, CD24+ cells are more differentiated luminal-type cancers and vaguer for the interpretation of BCSC markers." (PMID 31728117, 2019). "In the present study, we designed a targeted CD24-PEGylated Au-NPs to improve the cancer detection in both in vitro and in vivo investigations." (PMID 30607332, 2018). "mtDNA depletion triggers chemoresistance in cancer cell lines and is correlated with increase and decrease ofCD44 and CD24 positivity respectively in HGC-27 and MKN-45 GC cell lines." (PMID 29845783, 2018). "These cancer stem-like cells express important hepatic CSC markers such as CD24, CD44, CD117, CD133, ALDH, ABCG2, Oct4, and Nanog which were extensively reported before." (PMID 29848298, 2018). "These cancer stem cell markers, including CD24, CD44, CD117, CD133, ALDH, ABCG2, OCT4, and Nanog, were significantly higher in Hep3B sphere cells shown by qRT–PCR analysis." (PMID 29848298, 2018). "Stem cell markers CD133, CD44, ABCG2, Oct4, Lgr5, and CD24 are also highly expressed in cancer stem cells." (PMID 29422082, 2018). "The number of cells expressing pan-CD44, CD44v9, CD133, and CD24, all of which were reported to be markers of cancer stem-like cells in CRC, increased after disruption of C45 CTOSs." (PMID 29662620, 2018). "To test the cancer specificity of CD24 expression in primary UCB, we analysed mRNA expression levels of 30 primary UCB and matched adjacent histologically non-cancer tissues by qRT-PCR." (PMID 30327565, 2018). "CD24 has prognostic value in survival as a marker for cancer stem cells whereas CLDN3 and CLDN4 have been shown to regulate the epithelial to mesenchymal transition." (PMID 30383866, 2018). "The highgrade (basal-like, claudin-low) subtype CSCs of themedullary, metaplastic cancer category exhibit theCD44+/CD24-/low/ALDH1+ CSC phenotype." (PMID 29845782, 2018). "To determine which HMGB1 receptor(s) is involved in mediating cell invasion, we silenced four well-recognized HMGB1 receptors (RAGE, TLR2, TLR4, and CD24) individually by transiently transfecting specific shRNA oligos in Panc-1 cancer cells for 48 h." (PMID 29615080, 2018). "By using the optimal cut-off value of CD24 expression, the sensitivity and specificity of CD24 for cancer detection were 45.8% and 95.8%, respectively." (PMID 30327565, 2018). "Reflecting on expression of CD24 in normal progenitor cells, CD24 is frequently expressed on human cancer cells." (PMID 30044847, 2018). "The differential or concurrent expression of CD44 and CD24 markers has been used for identification of cancer stem cells (CSCs) in a variety of human epithelial and sarcomatoid renal cell carcinoma malignancies." (PMID 30648121, 2018). "Enhanced CD24 expression in various cancers, including PDAC, has been reported, and CD24 expression correlates with malignancy." (PMID 30410672, 2018). "It is suggested that the detection of CD24 as a crucial biomarker can help to improve the cancer treatment procedure." (PMID 30607332, 2018).
cancer (continued). "Similar to the human cancer patients, we found six of these seven models had reductions in absolute numbers of BM CD24+ cDC1s and most had reductions in the absolute number of BM pre-DCs." (PMID 29593283, 2018). "Different cancer stem cell populations were analyzed by flow cytometry using putative surface cancer stem cell markers (CD24, CD44 etc.).Metabolic phenotype varied between different grades of OSCC." (PMID 29460395, 2018). "This study was aimed to introduce a new contrast agent that was targeted with CD24 so as to improve the CT scan detection of cancer cells with higher CD24 expression." (PMID 30607332, 2018). "CD24 is worth further investigation as a novel biomarker for tamoxifen resistance beyond general aggressiveness of cancer cells." (PMID 29416796, 2018). "By determining the optimal cut-off using ROC curves for each molecule, the individual sensitivity and specificity of these six molecules (NANOG, CD49f, LGR5, ΔNp63, SOX2, and CD24) for cancer detection ranged from 29.2% to 62.5% and 83.3 to 100%, respectively." (PMID 30327565, 2018). "As an adhesion molecule, CD24 is widely expressed in many cancer types, including renal, ovarian, lung and pancreatic cancers." (PMID 28418843, 2017). "Functional studies demonstrated that HOXC8 gain of function induces a decrease in the CD44+/CD24-/low cancer stem cell population and proportion of chemoresistant cells, with a concomitant increase in CD24+ differentiated cells." (PMID 28202042, 2017). "We found that the expression levels of miR-31 are higher in the CD24+CD90+ cancer stem cells as compared to the CD24+CD90− cells." (PMID 29051494, 2017). "In this study, we first characterized the well-accepted cancer stem cell surface marker, including CD24, CD44 and CD133 in CSCs isolated by culturing panc-1 cells in serum-free medium." (PMID 28854261, 2017). "The combination of the transmembrane proteins CD44 and CD24 has been used to characterize the stemness of cancer cells over a long period of time." (PMID 29062075, 2017). "STAT3 activity is a well-established player in cancer stemness and, indeed, CD24-induced STAT3 activation in nasopharyngeal carcinoma cells triggers their reprogramming towards a CSC state." (PMID 28320418, 2017). "To further clarify the effect of RORβ on CCICs, we observed the tumorigenicity in vivo, the change in the colosphere number and the ratios of CD44 + CD24+ cancer-initiating cells in cells with overexpression of RORβ." (PMID 28137278, 2017). "Both Hes1 mRNA and protein levels were significantly reduced in CCR7-null cancer stem cell-like populations, either sorted for CD24+CD29hi expression by FACS or selected through culturing as secondary mammospheres." (PMID 28137279, 2017). "In this pair of comparison, the CD44+ cells had a higher potential of generating in peritoneal cavity of CD44high, CD44+CD24–, CD44+CD24+ cell subpopulations, highlighting the presence of cancer stem cells in a pool of CD44+ cells." (PMID 28622715, 2017). "In this study, it was shown that CD146 induced an increased expression of CD44 but also a decreased expression of CD24 on the cell membrane suggesting that cancer cells acquire a cancer stem cell-like phenotype." (PMID 31548532, 2017). "Furthermore, real-time PCR analysis showed knockdown of lncRNA XIST could markedly decrease the expression of many stemness-associated genes (Nanog, Oct-4 and SOX2) and surface antigens associated with cancer stem cells (CD24, CD44, CD133, CD155 and CD166) (*P<0.05)." (PMID 28837144, 2017). "Several cancer stem cell markers (CD24, CD133, and EpCAM) were highly expressed in Huh7/2% HUVECs-3D." (PMID 28874716, 2017). "mRNA and protein levels of the tumourigenic cancer stem cell markers CD24, CD133, EpCAM, and β-catenin were higher in the spheroids cultured with HUVECs." (PMID 28874716, 2017). "CD24 is a cancer stem cell (CSC) marker for PDAC which plays important roles in the carcinogenesis process of the pancreas." (PMID 28369074, 2017).
cancer (continued). "To study the sensitivity of BCSCs to 5-FU treatment, we firstly separated the cancer stem cell population of CD44+/CD24-/low phenotype in T-47D and SKBR3 cell lines." (PMID 29371950, 2017). "Surprisingly, DPI treatment selectively depleted the CSC sub-population (CD44+/CD24-) from the total cancer cell population." (PMID 29253841, 2017). "CD44-positive and CD24-positive cells have been proposed as predictors of prognosis and treatment response in BC, with clinical implications for cancer treatment because of their role in chemoresistance." (PMID 28399903, 2017). "Immunohistochemistry double-staining of CD44 and CD24 was also performed on paraffin-embedded primary NPC samples from patients at different stages of the cancer." (PMID 27521216, 2016). "The transcriptome of TICs freshly isolated from primary tumors by cell sorting was compared with that of sorted non-CD24+CD90+CD45− cancer cells by RNA-seq." (PMID 27542270, 2016). "Using SAGE-Seq libraries, we identified 2,145 genes that are differentially expressed in CD24+ cancer cells compared to CD24+ normal breast epithelium cells." (PMID 26673618, 2016). "We first purified CSCs by FACSort using the cancer stem cell markers ESA+CD24+CD44+; a marker for the murine MHC class I molecule, H-2Kd, was also included to enable identification and exclusion of murine stromal cells from the analysis." (PMID 27330806, 2016). "In this study we demonstrate that downregulation of the IGF1R specifically in cancer cells expressing CD24 on the cell surface membrane affect both their morphology (from mesenchymal-like into epithelial-like morphology) and phenotype in vitro." (PMID 27179633, 2016). "Using our in vitro model, we found that SOX2 expressing cells displayed several characteristics of cancer stem cells; such as a decreased proliferative rate, a spheroid growth pattern, and increased expression of stem cell markers CD24 and CD44." (PMID 27411517, 2016). "Studies have attempted to target CD24 with a monoclonal antibody (mAb) in several cancer models, including lung, ovarian, colorectal, and pancreatic cancer." (PMID 26891329, 2016). "CD90 is a hematopoietic stem cell marker that has been shown to label a subset of CD24+ cancer stem cells." (PMID 27542270, 2016). "CD24 can regulate both pro- and anti-proliferative effects in cancer cells, and both increase or reduce metastasis, depending on the cancer type." (PMID 28083532, 2016). "MCF7/C6 cells are with enrichment of cancer stem-cell like cells with positive staining of CD44+/CD24-/low, OCT3/4 and NANOG." (PMID 27036550, 2016). "CD24 has gained attention as a potential marker for putative cancer stem cells (CSCs) that, according to the CSC-concept, initiate and drive solid tumor growth." (PMID 26978528, 2016). "Upregulated CD24 expression has been reported for many types of human cancer, and its expression correlates significantly with different clinicopathologic properties." (PMID 26978528, 2016). "The results revealed much more CD44+/CD24-/low positive cells, indicating a high ratio of cancer stem cells in MCF7-ErbB2 cell which was also observed in the ALDH assay." (PMID 27416801, 2016). "Similar results were shown in the MKR tumors, where approximately 73 % of the cancer cells were CD24+ following implantation of the CD24+ control cells, and only approximately 10 % were CD24+ in the CD24+ IGF1R-KD tumors." (PMID 27179633, 2016). "At sacrifice, tumors were dissociated into single cells and cancer cells were FACS analyzed (based on their GFP expression) for CD24 expression." (PMID 27179633, 2016). "We further analyzed cancer stem cell markers, CD44, CD24 and CD133, associated with aggressive cancer types and poor prognosis in CRC." (PMID 27411517, 2016). "Our previous study has revealed the enrichment of HER2+/CD44+/CD24-/low cancer stem cell population in MCF7/C6 cells." (PMID 27036550, 2016).